STAT1 (signal transducer and activator of transcription 1)
Diseases named in the same sentence as STAT1 in open-access papers (continued):
Sharing a sentence is not in itself a finding about the gene and the disease.
gastric cancer (continued). "In gastric cancer, head and neck cancers, and cholangiocytes, IFNγ induces PD-L1 expression through the JAK/STAT1 pathway." (PMID 34445462, 2021). "IL-11, a member of the IL-6 family, promotes the progression of chronic inflammation to gastric carcinoma via gp130-mediated activation of STAT3 and STAT1 signaling in human gastric carcinogenesis." (PMID 34210998, 2021). "Trastuzumab-R27T induced robust STAT1 phosphorylation in both NCI-N87 and Hs746T gastric cancer cells harboring high and low HER2 expression, respectively." (PMID 33505314, 2020). "In this study, our results showed significant STAT1 overexpression in the ADAR1-knockdown AGS cell line, suggesting that STAT1 plays a tumor suppressive role and is downregulated by ADAR1-high in gastric cancer." (PMID 32867271, 2020). "To characterize MDSC infiltration in gastric cancer tissue, we defined MDSCs as CD33+/p-STAT1+ cells." (PMID 23307253, 2013). "EBNA1 was also found to upregulate STAT1 in HONE-1 NPC and AGS gastric carcinoma cells and to result in enhanced STAT1 phosphorylation and nuclear localization in response to IFNγ." (PMID 23170171, 2012). "For example, in gastric cancer, through a GTPase manner, TGM2 inhibits tripartite motif-containing protein 21 (TRIM21)-mediated ubiquitination and degradation of signal transducer and activator of transcription 1 (STAT1), and thus enhances its stability and oncogenic actions." (PMID 39115570, 2024). "Hypoxia also triggers the secretion of CXCL8 in TAMs that activates the C‐X‐C Motif Chemokine Receptor 1/2 (CXCR1/2) on the plasma membrane of gastric cancer cells further activating the Janus kinase 1/Signal transducer and activator of transcription 1 (JAK/STAT1) signaling pathway." (PMID 38703051, 2024). "In vitro, the interaction between STAT1 and the TRIM21 promoter was confirmed in 293FT cells, and in vivo, TRIM21 overexpression in MKN45 cells suppressed tumor growth in nude mice, aligning with its tumor-suppressive role in gastric cancer." (PMID 39768197, 2024). "In gastric cancer, elevated alpha-inducible protein 6 (IFI6) and FKBP prolyl isomerase 10 (FKBP10) could be responsible for the activation of STAT1 expression, diminishing antiviral responses." (PMID 39228892, 2024). "STAT1 transcription factor leads to the overexpression of IL‐10 that induces the immunosuppressive phenotype of TAMs and continues the overexpression of CXCL8 in a positive feedback loop aiding in the invasion and proliferation of gastric cancer cells." (PMID 38703051, 2024). "Since miR-302a-3p can target IRF9 by directly binding to its 3′UTR and miR-302-5p can weakly bind to STAT1 and indirectly regulate its expression, ADAR1-mediated miR-302a regulation might influence gastric cancer in an integrative manner." (PMID 38689093, 2024). "Relevant to both OSCC and EBV+-gastric cancer, JAK2/STAT1 signaling has been shown to mediate respectively EGFR- or IRF-1, IFNγ-induced upregulation of the programmed cell death-ligand 1 (PD-L1), an inhibitor of T-cell-mediated tumor cytotoxicity as discussed later in this review." (PMID 35844493, 2022). "Taken above, there may exist an interplay between STAT3 and STAT1 regulated by OSM, and the different transformations between them may affect the progress of gastric cancer." (PMID 31871447, 2019). "Additionally, in a mouse model of gastric cancer, it was observed that HDAC3 may induce B7-H1 expression by activating the JAK/STAT1 pathway." (PMID 40006729, 2025). "However this view was challenged recently by reports showing STAT1 was involved in radioresistance and as a promoter and not a suppressor in breast and gastric cancer cells." (PMID 30131584, 2019). "These CD33+/p-STAT1+ double-positive cells have been found mostly in the stroma among gastric cancer, whereas they had not yet been observed in the normal mucosa adjacent to gastric cancer and normal mucosa far from the gastric cancer (data not shown)." (PMID 23307253, 2013).
lupus (58 papers, 2008 to 2025). "In sharp contrast, STAT1 deficiency protected mice against pristane-induced lupus, as evidenced by increased survival, low titers of anti-dsDNA IgG, and less severe nephritis in the STAT1 knockout mice compared to their T748A littermates." (PMID 39329714, 2024). "Moreover, STAT1 deficiency in the lupus-like chronic graft-versus-host disease model led to a prolonged but amplified increase of anti-dsDNA IgG in sera and also higher proteinuria and mortality." (PMID 28620377, 2017). "Clarifying this relationship will require further experimental studies using lupus-prone animal models with B cell-specific manipulation of STAT1." (PMID 40744996, 2025). "In vivo, lupus mice in which JAK/STAT1 or CCL8 signaling was inhibited were largely protected from depression and synapse loss." (PMID 40048256, 2025). "In systemic lupus erythematosus (SLE), PKCδ deficiency results in impaired B cell apoptosis, loss of immune tolerance, and subsequent disease progression, while indirectly participating in SLE‐associated inflammatory responses through regulation of the IFN/STAT1 pathway." (PMID 41244006, 2025). "We have previously shown that C57 black mice are susceptible to pristane-induced lupus by an NCF1-associated effect, mediated by hyperactive plasmacytoid dendritic cells (pDCs) by activating type I interferon and STAT1 pathways." (PMID 39939342, 2025). "For instance, gain-of-function (GOF) mutations in STAT1 amplify IFN-α/β signaling, predisposing to disorders ranging from autoimmune thyroiditis to systemic lupus erythematosus." (PMID 40831950, 2025). "Through genetic and biochemical assays, we demonstrate that Thr748 phosphorylation is dispensable for STAT1 functionality in pristane-induced lupus." (PMID 39329714, 2024). "STAT1 is critical in inflammatory diseases, such as systemic lupus erythematosus, inflammatory bowel disease, and psoriasis." (PMID 38321132, 2024). "Our findings show that Stat1 drives the pathology of pristane-induced lupus independently of the Thr748 phosphorylation." (PMID 39329714, 2024). "Our data confirm the regulation of STAT1, a transcriptional factor for ISGs, at the early stage of pristane‐induced lupus." (PMID 39120068, 2024). "To address this point, we compared the lupus severity of T748A and Stat1 knockout (hereafter referred to as KO) female littermates following pristane injection." (PMID 39329714, 2024). "Our observations show that the Thr748 phosphorylation of STAT1 is dispensable for survival and autoantibody production in pristane-induced lupus." (PMID 39329714, 2024). "The simplest interpretation of these observations is that Thr748 phosphorylation is dispensable for STAT1-mediated pathology in pristane-induced lupus, indicating that Thr748 phosphorylation modulates Stat1 activities in a context-dependent manner." (PMID 39329714, 2024). "Using pristane-induced lupus, a prototype systemic interferonopathy, we show that Stat1 mediates lupus pathology independently of Thr748 phosphorylation." (PMID 39329714, 2024). "Having found that ROS-deficient pDCs displayed increased IFN-α production and type I IFN responses via the STING and JAK1/STAT1 pathways, we further investigated if these hyperreactive cells exacerbate lupus." (PMID 36853827, 2023). "The remaining four patients had the following autoimmune interferonopathies: 2/4 systemic lupus erythematosus (SLE), 1/4 juvenile dermatomyositis (JDM), 1/4 autoimmune hepatitis with a detected gain-of-function mutation in STAT1." (PMID 35573950, 2022). "IRF1, IRF8, and STAT1 are important in human inflammatory diseases including systemic sclerosis, systemic lupus erythematosus, and inflammatory bowel disease." (PMID 36091020, 2022).
lupus (continued). "For example, although STAT1 mRNA levels are both increased in lupus and normal CD8+ T cells with IFN-α stimulation, the signature of hypomethylated DNA sites in lupus CD8+ T cells facilitates the upregulation of HLA-DRB1 in a STAT1-signaling-dependent manner." (PMID 34305954, 2021). "The cytokine network type I IFN–IL-27–IL-10 is augmented in murine and human lupus, and IL-27 induces T-bet expression via STAT1 signaling and class switching in B cells." (PMID 34504495, 2021). "STAT1 levels in CD4+ T cells from lupus patients are higher than from rheumatoid arthritis patients and healthy subjects and positively correlate with disease activity, with highest levels in CD45RA-FOXP3hi-activated Tregs (aTregs)." (PMID 33271810, 2020). "STAT1 serine-727 phosphorylation (designated STAT1-pS727) plays an important role in promoting Tfh cell responses, leading to systemic lupus erythematosus- (SLE-) associated autoantibody production." (PMID 32766317, 2020). "Ex vivo, in systemic lupus erythematosus patients, higher levels of ISG15 are associated to reduced STAT1 phosphorylation in response to IFNα, and also to increased frequencies of Tregs, characterising active disease." (PMID 33376595, 2020). "We observed that the increased levels of autoantibodies in the lupus mice were significantly reduced in dendritic cells that were pretreated with the STAT1 inhibitor or p38 MAPK inhibitor compared to those that were pretreated with the corresponding control." (PMID 32296043, 2020). "Activation of STAT1 was also identified in other skin diseases, such as systemic lupus erythematosus and psoriasis." (PMID 32544098, 2020). "Meanwhile, IFN-γ has been identified to stimulate IDO production in MSCs via the STAT1 signaling pathway, contributing to an enhanced immunosuppressive capacity of normal MSCs inhibiting the proliferation of lupus T cells." (PMID 29793537, 2018). "The same study further confirmed that in in vitro, over expression of miR-146a reduced the expression of STAT-1 which correlates with the earlier reports from lupus patients and in a mouse model where expression and activation of STAT-1 was reported." (PMID 31557989, 2016). "Recent studies have revealed a positive correlation of miR-146a with STAT1, which is involved in the type I IFN pathway, and polymorphism studies have confirmed its role in lupus." (PMID 25988383, 2015). "Although distinguished phenotypically, this included non-lupus-related features such as dysmorphism and developmental delay and infection arising as part of the complex phenotype of the causal variants identified (MAN2B1, SLC7A7, PTEN, STAT1)." (PMID 40465409, 2025). "Thus, our ex vivo analysis indicates that the Thr748 phosphorylation is dispensable for Stat1-mediated lupus pathology following pristane injection." (PMID 39329714, 2024). "By measuring LN, we examined whether the Thr748 phosphorylation of STAT1 contributes to the severity and progression of pristane-induced lupus." (PMID 39329714, 2024). "Moreover, p38 MAPK or STAT1 inhibitor treatment also abolished the enhanced effect of sodium chloride on the dendritic cell-initiated lupus model." (PMID 32296043, 2020). "T cells of lupus patients showed poor response of STAT1, STAT3 and STAT5 to IFNα." (PMID 33271810, 2020). "The JAK2/STAT1 pathway mediates the renal damage in lupus models induced by anti-dsDNA antibodies." (PMID 28620377, 2017). "Mechanistic analyses in our study revealed elevated expression of phosphorylated STAT1 and STAT3 in T2DM patients, where these phosphoproteins were also implicated in the pathogenesis of autoimmune diseases such as rheumatoid arthritis, systemic lupus erythematosus, and psoriasis." (PMID 41030441, 2025). "A phase 2 study with baricitinib in patients with systemic lupus erythematosus (SLE) showed a significantly higher expression of the STAT1 gene in SLE patients who had active disease at study entry." (PMID 35958600, 2022).
lupus (continued). "We found that in the brains of lupus mice, IFN-γ–regulated genes are highly expressed, IFN-γ induces neurons to secrete CCL8 via JAK/STAT1 signaling, and microglia are activated and show increased phagocytosis following entry of IFN-γ into the brain." (PMID 40048256, 2025). "Our present study further demonstrated that STAT1 and ETS1 were hub TFs in the tubulointerstitium, which provided evidence for the interaction of TFs in lupus." (PMID 36829595, 2023). "The RhoA/ROCK inhibitor in turn reduced type I IFN-induced STAT-1 phosphorylation and ISRE reporter gene expression, as well as OAS1 and CXCL10 in human lupus PBMCs." (PMID 37790522, 2023). "Increased numbers of pDCs, together with their hyperactivation via stimulator of interferon genes (STING)/IFN-α/JAK1/STAT1 signaling, resulted in higher IFN-α levels and ISG expression, explaining the impact of NCF1-derived ROS on lupus severity." (PMID 36853827, 2023). "STAT1 and RELA (p65) are hub differential TFs between LN and normal kidneys, and the differential TFs in lupus renal tissues were mainly enriched in T-cell-related signaling." (PMID 36829595, 2023). "Of importance, here we showed that hyperactivated IFN-α/JAK1/STAT1 signaling, in concert with increased STING-dependent IFN-α production in Ncf1m1j/m1j pDCs, acting as a positive feedback loop, augments type I IFN responses, which may be crucial to lupus exacerbation driven by ROS deficiency." (PMID 36853827, 2023). "With respect to ISGF3, in a mouse model of pristane-inducible IFN-driven lupus, both IRF9 and STAT1 were shown to be required for autoantibody production and development of kidney disease." (PMID 30984161, 2019). "Both STAT1 and STAT4 have been reported to be related to autoantibody production and renal involvement in either lupus mice or SLE patients." (PMID 29793537, 2018). "Negative regulation of type I IFN through TLR-7 pathway by miR-146a was identified to inhibit the expression of STAT-1 and interferon regulatory factor 5 (IRF-5) in systemic lupus erythematosus (SLE) patients." (PMID 31557989, 2016). "This revealed that three prioritised lupus genes (USP18, STAT1, IFNA1-17) were shared with the 13 category I genes (IFNAR1/2 signal transduction proteins) and four prioritised genes (IRF1/5/8 and OAS1) were shared with the 38 category II genes (transcriptional targets of interferon response)." (PMID 41038828, 2025). "We identified two transcription factors (STAT1 and LTF) that were positively correlated with T-cell subset infiltration in the lupus tubulointerstitium, and three transcription factors (IRF8, RORC and IKZF2) that were positively associated with T-cell subset infiltration in the glomeruli." (PMID 36829595, 2023). "According to current studies, a critical functional link between miRNAs and the lupus CD4+ T cells have been connected by the potential interplay between miRNAs and critical molecules such as SLAM family, STAT-1, DNMT1 which contribute to T cells abnormalities and hypomethylation in SLE." (PMID 34408748, 2021). "Changed phenotype of CD8+ T cells in lupus, and altered response to type I IFN, may indicate dysregulated STAT1 signaling in these cells." (PMID 33271810, 2020). "STAT1 has been reported to be upregulated in peripheral blood mononuclear cells from SLE patients and in kidneys of lupus mice with nephritis, suggesting that STAT1 may play a role in the pathogenesis of SLE." (PMID 18803832, 2008). "Transplanted hUCMSCs targeted Th1 cell–derived IFN-γ to inhibit neuronal JAK/STAT1 signaling and downstream CCL8 expression, reducing phagocytic microglia apposition to alleviate synaptic engulfment and neurological dysfunction in young (8-week-old) lupus mice." (PMID 40048256, 2025). "In this study, we employed Mendelian randomization to investigate the potential causal relationship between five genes, namely, DDX58, IFIH1, IRF7, STAT1, and ISG15, and systemic lupus erythematosus (SLE)." (PMID 39445158, 2024).
lupus (continued). "We then investigated whether the lack of requirement for Thr748 phosphorylation of STAT1 in the observed lupus pathology is due to its dispensability for STAT1 function in the pristane-induced lupus model, or whether pristane fails to induce Thr748 phosphorylation in Wt mice as well." (PMID 39329714, 2024). "The role of miR-146a in targeting Stat1 in human T cells is also supported by the study of systemic lupus erythematosus (SLE) patients: in the PBMCs of these patients, a decreased miR-146a expression was observed, responsible for the induction of type I IFN through Stat1 and IRF5 targeting." (PMID 29657293, 2017). "In this experiment, BMDCs were treated with a STAT1 inhibitor or p38 MAPK with or without sodium chloride, and then BMDC-ALD-DNA was transferred into normal mice to induce lupus under a normal-salt diet (NSD)." (PMID 32296043, 2020). "Moreover, we treated STAT1 knockout BMDCs with NaCl and found that NaCl did not facilitate BMDCSTAT1−/−-ALD-DNA-induced murine lupus and that NaCl did not exacerbate the activation and maturation of BMDCs in vitro." (PMID 32296043, 2020).